MIR618 (microRNA 618)
Synonyms: hsa-mir-618; MIRN618; mir-618
Gene: MicroRNA gene on chromosome 12 (80,935,736 to 80,935,833, reverse strand). Ensembl gene ENSG00000208022.
Gene Ontology:
Biological process: miRNA-mediated post-transcriptional gene silencing
Cellular component: RISC complex
Diseases named in the same sentence as MIR618 in open-access papers:
MIR618 is named in the same sentence as 2 diseases in open-access papers, as found by Europe PMC text mining. Sharing a sentence is not in itself a finding about the gene and the disease. The quoted sentences say what the papers report.
breast carcinoma (1 paper, 2024). "In general, this variant in the MIR618 gene has been associated with the regulation of miR-618 expression and has implications for susceptibility and progression of various diseases, including breast cancer, colorectal carcinoma, and metastatic colon cancer." (PMID 39596593, 2024).
MIR618 also shares sentences with these, for which no sentence is quoted: colorectal carcinoma (1 paper).